INS (insulin)
Diseases named in the same sentence as INS in open-access papers (continued):
Sharing a sentence is not in itself a finding about the gene and the disease.
diabetic nephropathy (continued). "Thus, RAPA may suppress diabetic nephropathy through both direct inhibition of mTORC1 and suppression of circulating insulin elevation." (PMID 35986566, 2022). "INS rs3842753 with a derived allele frequency of more than 75% in non-African populations has been identified as a marker for atypical T2D in the Uruguayan population, while IGF2 rs10770125 has been associated with diabetic nephropathy in people with European American ancestry." (PMID 32171244, 2020). "Therefore, vitamin D might slow down diabetic kidney disease progression by delaying destruction of b-islet cells, enhancing insulin secretion, and consequently assisting in glucose metabolism." (PMID 28497094, 2017). "Thus, the beneficialactions of insulin in diabetic nephropathy appear to be mediated, in part, bysuppressing renal Nrf2 and Agt gene transcriptionand preventing Nrf2 stimulation of Agt expression via hnRNP F/K.These findings identify hnRNP F/K and Nrf2 as potential therapeutic targets indiabetes." (PMID 28324005, 2017). "Because insulin signaling may be required not only for the nitric oxide (NO) production by glomerular endothelium but also for the preservation of normal podocyte functions, insulin resistance in glomeruli may promote the occurrence and progression of diabetic nephropathy." (PMID 24982885, 2014). "The accelerated pyruvate utilization flux after insulin administration indicates that the metabolic disturbances in the diabetic kidney during poor glycemic control are limited by substrate availability, possibly indicating a novel therapeutic target to treat diabetic nephropathy." (PMID 25501426, 2014). "Defects in insulin signalling may contribute to diabetic kidney disease." (PMID 20604929, 2010). "During the analysis of lipotoxicity in diabetic kidney disease, global fatty acid transport protein 2 (FATP2) gene deletion was noted to markedly reduce plasma glucose in db/db mice due to sustained insulin secretion." (PMID 40956612, 2025). "In diabetic kidney disease (DKD), SGLT2 inhibitors slow progression by improving glycemic control through increased insulin sensitivity and glucose excretion, reducing albuminuria, and slowing the decline in estimated glomerular filtration rate (eGFR)." (PMID 40517274, 2025). "The levels of hsa-miR-221 positively correlated with the BMI, serum fasting insulin, serum fasting glucose, HOMA IR, and urinary ACR in the diabetic nephropathy group." (PMID 37831346, 2023). "Diabetic nephropathy may be delayed / prevented by IR knockout, or rapamycin treatment, or curtailing podocytes’ mTORC1 copies, or by suppressing Akt activity in proximal tubular cells, implying a role for insulin-activated mTORC1 in driving diabetic nephropathy." (PMID 32128655, 2020). "As expected, the KK-Ay mice developed symptoms of diabetic nephropathy at 8−9 weeks of age, with significant increases in UACR, Ualb excretion, plasma glucose, and insulin concentrations compared with the respective outcomes in the control C57BL/6 J mice." (PMID 32616846, 2020). "It was found that the TGF-β1 pathway, AMPK signaling pathway, insulin-related signaling pathway, lipid metabolism, and TNF-α pathway were the major pathways of treatment of GDC for diabetic nephropathy." (PMID 29853965, 2018). "The main action pathways closely related to the development of diabetic nephropathy were the TGF-β1, AMPK, insulin, TNF-α, and lipid metabolism pathways as per network pharmacology analysis." (PMID 29853965, 2018). "We previously demonstrated that podocytes are insulin-responsive cells in vitro, and the specific deletion of the podocyte insulin receptor (IR) in vivo disrupts glomerular function, causing features reminiscent of diabetic nephropathy, independent of hyperglycaemia." (PMID 28852804, 2017). "Soluble CD36 is a biomarker of T2D and diabetic nephropathy and coordinates activation of the NLRP3 inflammasome, leading to proinflammatory cytokine release and reduced insulin secretion." (PMID 27864352, 2017).
diabetic nephropathy (continued). "The likely mechanism for this diabetic nephropathy-like phenotype in PodIRKO mice was reduced VEGF-A production, which is stimulated by insulin in podocytes in vitro and in vivo." (PMID 27514532, 2016). "Effect of FPS on the ratio of the weight of the kidney to body weight, renal function, serum insulin, glycosylated hemoglobin, microalbumin and β2-microglobulin in the STZ-induced diabetic nephropathy rats." (PMID 24886867, 2014). "Indeed, quercetin can help prevent AGE accumulation and reduce diabetic nephropathy, while resveratrol activates the SIRT1 pathway, improving insulin sensitivity." (PMID 41150789, 2025). "Of note, GWAS has some limitations, as: a) miRNAs are rarely prioritized in GWAS due to their regulatory roles, but transcriptomic studies link miR-342-5p to insulin signaling (e.g., suppression of IRS1 in adipose tissue) and miR-636 to autophagy in diabetic nephropathy." (PMID 40533788, 2025). "The patients included in these studies comprised men and women aged 54–61 years old, insulin- and noninsulin users, with accompanying diseases such as chronic renal failure, diabetic nephropathy, and coronary heart disease." (PMID 38790901, 2024). "Since beta cells are the key cells leading to T2D, we search for hub genes in CCSN of beta cells and find that ATP6AP2 is essential for regulation and storage of insulin, and the renin-angiotensin system involving ATP6AP2 is related to most pathological processes leading to diabetic nephropathy." (PMID 35885938, 2022). "In addition to ameliorating insulin assistance, SIRT1 has also been known to promote the activation of the Nrf-2/ARE pathway and improve oxidative stress in diabetic nephropathy." (PMID 34845191, 2021). "UACR, Ualb, blood glucose, and insulin levels were all increased significantly in KK-Ay mice compared with the respective levels in C57BL/6 J mice at 8–9 weeks of age, indicating that KK-Ay mice developed diabetic nephropathy." (PMID 32616846, 2020). "The impairment of IRS2 signaling in the podocyte in the onset of diabetic nephropathy has been very recently suggested; Santamaria and colleagues demonstrated that phosphatase and tensin homolog (PTEN) and IRS2 were essential for insulin signaling in podocytes." (PMID 27247938, 2016). "The multipronged drug approach targeting blood pressure and serum levels of glucose, insulin, and lipids fails to fully prevent the onset and progression of diabetic nephropathy." (PMID 24455746, 2013). "Similarly, treatment with BAY 41–8543 or BAY 60–2770 did not affect plasma insulin levels in non-diabetic nephropathy rats." (PMID 39494352, 2024). "For example, DHM was reported to mediate the AMPK-PGC-1a-SIRT3 signaling pathway to improve skeletal muscle insulin sensitivity and promote autophagy by activating AMPK/mTOR signaling pathway, thereby reducing diabetic kidney injury and even delaying the progression of diabetic nephropathy." (PMID 38275711, 2024). "In other insulin-sensitive, as well as fibrosis-prone organs, such as the liver, heart, and visceral adipose tissue, Thy-1 mRNA expression was not affected in this model of diabetic nephropathy." (PMID 36768219, 2023). "Moreover, in a study not included in the previously cited meta-analysis, CoQ10 supplementation at a dosage of 100 mg/day for 12 weeks had positive effects on insulin metabolism and MDA levels among diabetic nephropathy patients yet fasting glucose remained unchanged." (PMID 32331285, 2020). "However, this may just indicate that modest improvements in insulin secretion later in disease are not sufficient to alter the progression of diabetic kidney disease." (PMID 31541173, 2019). "High glucose level, either due to resistance of cells to insulin or lack of insulin synthesis, plays an important role in production of ROS through the activation of various cellular responses thereby leading to deleterious effects like diabetic kidney disease." (PMID 28497094, 2017).
diabetic nephropathy (continued). "Similarly, DMY could also mediate the AMPK-PGC-1α-SIRT3 signaling pathway to improve skeletal muscle insulin sensitivity and promote autophagy by activating the AMPK/mTOR signaling pathway, which can alleviate diabetic kidney injury and even retard the progression of diabetic nephropathy." (PMID 37732125, 2023). "The effect of diabetic nephropathy and diabetic neuropathy on NPDR development were not significant after adjusting with OHA and insulin control." (PMID 30133506, 2018).
neuropathy (262 papers, 2005 to 2026). A disorder affecting the nervous system that manifests with pain, tingling, numbness, and/or muscle weakness. "This reduced risk is partially explained by lower levels of PAD, neuropathy, insulin usage and foot deformities in South Asians, which appears to account for about half of the observed reduction in foot ulcer risk." (PMID 40555701, 2025). "The absolute or relative deficiencies of insulin and insulin resistance contribute to the development of various metabolic and vascular diseases, neuropathies, and pathological changes in internal organs and tissues, including the digestive system." (PMID 37110171, 2023). "MGO is a strong inducer of AGE formation and RAGEs, and it has been linked to insulin resistance, vascular dysfunction, and neuropathies." (PMID 36235696, 2022). "A pre-diabetic condition occurs if the values of insulin and or insulin and glucose are increased, which results in an increased risk of developing macrovascular diseases and neuropathy." (PMID 35056318, 2021). "We concluded that a mild acute neuropathy with inflammatory components was induced in BB/OKL rats as a consequence of the abrupt decrease in HbA1c caused by high-dose insulin treatment." (PMID 34639176, 2021). "We conclude that a mild acute neuropathy with inflammatory components was induced in BB/OKL rats as a consequence of an abrupt decrease in HbA1c caused by high-dose insulin treatment." (PMID 33557206, 2021). "By treating diabetic BB/OKL rats with an insulin dose, causing an abrupt decrease in HbA1c levels, we were able to induce an acute form of neuropathy." (PMID 33557206, 2021). "In accordance with the published studies, the SIDD cluster had the highest prevalence of retinopathy and neuropathy, and the insulin resistant subgroups were linked to high risk of CKD." (PMID 34276762, 2021). "Altered insulin signaling has been linked to widespread nervous system dysfunction including cognitive dysfunction, neuropathy and susceptibility to neurodegenerative disease." (PMID 27525480, 2016). "Independent risk factors for TDHS include poorly controlled diabetes, neuropathy, insulin treatment or malnutrition." (PMID 22891082, 2012). "The findings of the present study showing insulin-induced TRPV4 channel sensitization may provide further insights into the mechanisms underlying acute insulin treatment-induced neuropathy after intensive glycemic control." (PMID 40343778, 2025). "The literature suggests that regular physical activity may reduce the risk of neuropathy, possibly by improving insulin sensitivity, endothelial function, and reducing systemic inflammation." (PMID 40801171, 2025). "Pioglitazone significantly reduces the neuroinflammation response and cerebral oxidative stress and, so, might play a neuroprotective role associated with improvements in inflammation-related neuropathy and insulin signalling pathways." (PMID 36830783, 2023). "In type 1 diabetes, intensive glucose control protects against neuropathy development, and insulin deficiency might contribute to neuropathy since insulin has a neurotrophic effect." (PMID 35329999, 2022). "Dietary reversal, whereby B6-wt mice fed a HFD from 4-20 weeks of age were switched to standard chow for 4 weeks, completely normalized neuropathy, promoted weight loss, improved insulin sensitivity, and restored LDL cholesterol and oxLDL by 50% compared with levels in HFD control mice." (PMID 28381495, 2017). "The current study supports the role of insulin and its impairments in the development of neuropathy and underlines that other parameters, in addition to insulin deficiency or resistance, might predispose the PNS and/or the CNS to damage." (PMID 24764191, 2014). "Notably, other factors can interfere with the association between insulin use and fractures, such as the duration of the disease and the coexistence of complications, including diabetic microvascular disease, retinopathy, and neuropathy." (PMID 39063229, 2024).
neuropathy (continued). "Demographic characteristics, metabolic parameters, and medication use (statins, fibrates, insulin, and neuropathy drugs) were retrieved from the hospital records." (PMID 41578556, 2026). "Stratification according to feet and hand ESC categories revealed a stepwise decline in eGDR across neuropathy stages, consistent with a dose–response relationship between insulin resistance and sudomotor dysfunction." (PMID 41257477, 2025). "ALA acts as a potent antioxidant and has been found to improve glycaemic control, insulin sensitivity and alleviate diabetic complications such as neuropathy and cardiovascular diseases." (PMID 40207422, 2025). "Our results are consistent with previous studies showing improved measures of neuropathy in patients on insulin pump therapy which of course is a key driver of diabetic foot ulceration." (PMID 40390300, 2025). "The sex-dependent differences in metabolism, including glucose dysregulation, lipid changes, and insulin signaling, demonstrate the complex interplay between aging, sex, and neuropathy." (PMID 41158618, 2025). "These plant derived compounds, resveratrol and plant based insulin mimetics, not only address metabolic dysfunction but also offer holistic treatment for long term complications such as neuropathy and retinopathy." (PMID 40191975, 2025). "On the other hand, neuropathy complications were found in 28 patients, all of whom were on insulin therapy." (PMID 39295783, 2024). "We found that, overall, participants from the new dataset had significantly lower TBR, TIR, GRI and HbA1c, more frequently used pumps and automated insulin delivery systems and had less frequent retinopathy and neuropathy." (PMID 38780786, 2024). "Specifically, higher rates of retinopathy (64.3%) and neuropathy (11.4%) were observed in the insulin group (69.9%) in the metformin group (11.4%)." (PMID 39495998, 2024). "Glycemic control with insulin has little effect on neuropathy in patients with T2DM given the insulin resistance developed by the neurons, similar to that of the muscle and adipose tissue." (PMID 37223297, 2023). "Improving blood sugar control using insulin and antidiabetic medication (oral solution) are proven strategies for decreasing the severity of neuropathy." (PMID 37845651, 2023). "Significant differences of patients’ characteristics by sex were observed for marital status (p = 0.005), neuropathy complication (p = 0.029), ever hospitalised (p = 0.043), use oral hypoglycaemics tablets (p ≤ 0.0001), and insulin (p ≤ 0.0001) medication." (PMID 37239611, 2023). "Although altered insulin signaling is a major factor in the development of DM, its role in DM neuropathy is not well understood." (PMID 35199097, 2022). "Cases of neuropathy are also disproportionately found in those who omit insulin; Steel and colleagues (1987) found that of the nine participants in their sample who admitted to IO, 5 (55.5%) displayed symptoms of neuropathy." (PMID 34121470, 2021). "These factors include long-standing diabetes, poor glycemic control, presence of GL, the time from the clinical diagnosis of lipodystrophy, insulin use, neuropathy, PAD, retinopathy, and diminished renal functions." (PMID 34593051, 2021). "The previous trial by diabetic complications and the research group showed that early intensive insulin therapy reduced neuropathy symptoms compared to conventional treatment." (PMID 34268025, 2021). "These include lack of clinical details such as hemoglobin A1c values, pharmacotherapeutic profile (use of insulin, anti-diabetic medications), and granular details about the ulcer (size, depth, etc.), neuropathy, and procedures." (PMID 32878057, 2020). "This phenomenon, known as “insulin neuritis” or “treatment-induced neuropathy,” has been reported in both type 1 and type 2 diabetic patients treated with insulin or oral hypoglycemic agents, who typically had a history of poor glycemic control." (PMID 31824259, 2019).